INS (insulin)
Diseases named in the same sentence as INS in open-access papers (continued):
Sharing a sentence is not in itself a finding about the gene and the disease.
Insulin resistance (continued). "Insulin is a strong suppressor of adipose lipolysis, therefore, defects of the insulin signaling in insulin resistance enhance lipolysis." (PMID 35563490, 2022). "In that study, adipose tissue insulin resistance was elegantly measured, using state-of the-art tracer methods to determine the insulin concentration necessary to suppresses adipose tissue lipolysis by 50% (IC50)." (PMID 35480482, 2022). "Insulin resistance, defined as a decreased efficiency of insulin action on its target tissues, is a major feature of metabolic diseases, leading to impaired glucose clearance and chronic hyperglycaemia." (PMID 36058931, 2022). "Because of the great importance of the insulin signal transduction pathway in insulin resistance, we further elucidated the effect of CSNO on the insulin signaling pathway." (PMID 36313766, 2022). "Insulin sensitivity was determined using a homeostasis model assessment of insulin resistance index (HOMA-IR)." (PMID 35454339, 2022). "MammaBlagosklonny19lian target of rapamycin (mTOR) inhibitors can induce insulin sensitivity or insulin resistance." (PMID 35893294, 2022). "In mice, HFD enabled the increase in the levels of LECT2, and the overproduced LECT2 further impaired insulin sensitivity and induced insulin resistance in skeletal muscle cells." (PMID 35656863, 2022). "Rather than stimulating insulin release, SGLT2 inhibitors improve β-cell function by improving glucotoxicity, as well as reduce insulin resistance and increase insulin sensitivity." (PMID 35614469, 2022). "Enhanced insulin secretion by β cells can counterbalance the increased resistance to insulin action; however, if β cells fail to compensate for insulin resistance, type 2 DM develops." (PMID 35052857, 2022). "Insulin resistance is defined as an impaired response of the body to insulin action, despite insulin being at a higher or normal level." (PMID 35562924, 2022). "Previous clinical attempts on known therapeutic targets for DCI, such as depleted insulin secretion, insulin resistance, and hyperglycaemia have delivered poor patient outcomes." (PMID 35899118, 2022). "Consistently, heterozygous TNFAIP3 depletion reversed the improved glucose metabolic abnormalities and insulin resistance resulting from GPSM1 deficiency, as revealed by glucose-tolerance tests and insulin-tolerance tests." (PMID 36434066, 2022). "T2D patients do not usually require exogenous insulin administration, and if they do, it is typically in late stages when endogenous insulin production is insufficient in the support of alternative treatments in overcoming the peripheral insulin resistance." (PMID 35055022, 2022). "Mitochondrial dysfunction was reported to interact with insulin resistance, and insulin signaling enhances mitochondrial gene expression and protein synthesis." (PMID 36380075, 2022). "T2DM is the more common type of DM, and it is primarily manifested by insulin resistance or relatively insufficient insulin secretion." (PMID 36561297, 2022). "A previous study showed the roles of the angiopoietin-like protein 8 regulatory pathway and insulin signaling pathway in enhancing glucose tolerance and insulin sensitivity under insulin resistance conditions." (PMID 35273637, 2022). "It is reported that an increased triglyceride level is associated with lipotoxic intermediate metabolites that inhibit insulin signaling and, ultimately, insulin resistance and obesity." (PMID 36582536, 2022). "Insulin resistance and impaired insulin signalling are common pathological mechanisms connecting T2D and AD." (PMID 36555450, 2022). "This oxidization contributes considerably to the T2D pathology, possibly by activating alternative downstream signaling pathways critically involved in insulin resistance and compromised insulin secretion." (PMID 36632095, 2022). "SIRD was the smallest subgroup in Indians with high insulin resistance as well as insulin secretion, although it was heterogeneous between the Indian cohorts." (PMID 34689214, 2022).
Insulin resistance (continued). "Insulin resistance is a pathological condition in which cells fail to sense and respond normally to insulin, with decreased insulin/insulin-like growth factor 1 (IGF-1) signaling (IIS)." (PMID 36465171, 2022). "The effect of SGLT2i treatment on hepatic insulin clearance and insulin resistance is not well known." (PMID 35115614, 2022). "It was discovered that when mice with insulin resistance were given melatonin, a powerful antioxidant, as a mealtime shift, their insulin levels returned to normal." (PMID 35343087, 2022). "Many of the pathways were involved in glucose metabolism, including insulin signaling pathway and insulin resistance." (PMID 36111143, 2022). "In mice, baked chow diets high in AGEs led to impaired insulin secretion, insulin resistance and T2DM, and arterial stiffness." (PMID 35133989, 2022). "Nrf2 translocation increased in the insulin resistant animals but decreased in the 2-week and 6-month diabetic hearts suggesting that Nrf2 is functional during insulin resistance but becomes dysregulated shortly after the onset of T2DM." (PMID 35624791, 2022). "Our results showed that TLB significantly reduced the high fasting blood glucose level and insulin resistance and promoted the tolerances to exogenous glucose and insulin in KK-Ay mice." (PMID 35153796, 2022). "One such study focused on an Inuit population, and found that increased use of cannabis resulted in lower levels of BMI, % fat mass, fasting insulin, and insulin resistance." (PMID 35328862, 2022). "Maternal indicators of insulin levels, insulin resistance, or sensitivity were related with CpG sites located in genes whose functions include brain development and regulation of insulin processes." (PMID 36137169, 2022). "Other mechanisms of insulin resistance include the reversion of the insulin-induced tyrosine phosphorylation of IRS-1, IRS degradation and decreased GLUT-4 expression." (PMID 35327570, 2022). "As insulin promotes glycolysis and suppresses lipolysis and proteolysis, these findings have been partially attributed to insulin resistance." (PMID 36243866, 2022). "The first problem is related to the wide variability in insulin sensitivity between subjects, some of who show a common overlap of insulin levels like those of insulin resistance." (PMID 35456928, 2022). "Overall, insulin resistance increases the level of insulin in circulation, and insulin is a growth factor that can promote tumor growth, which accelerates the process of cachexia." (PMID 36105371, 2022). "High serum insulin and leptin levels are early indicators of insulin resistance and impairments in glucose metabolism/prediabetes." (PMID 35807769, 2022). "T2DM is distinguished by three major defects: abnormal pancreatic insulin secretion, increased hepatic glucose uptake, and peripheral insulin resistance." (PMID 36355489, 2022). "The obtained results confirm that the HFD induces the development of whole-body insulin resistance, which results in inhibition of the insulin pathway." (PMID 35406688, 2022). "Many tests are used to assess insulin resistance, such as Quicki test, insulin sensitivity index, etc., but the HOMA-IR index is most used in daily visits and epidemiological studies." (PMID 35974947, 2022). "The body mass index (BMI), blood glucose concentration, serum insulin level, and homeostasis model assessment of insulin resistance (HOMA-IR) of the intervention group decreased significantly after the weight reduction intervention." (PMID 36531452, 2022). "The consequence of hyperinsulinemia compensatory to insulin resistance is an overstimulation of non-insulin-sensitive tissues, such as the ovaries." (PMID 35456928, 2022). "In T2DM, insulin resistance produces AGEs due to oxidative stress, which leads to glucotoxicity and disruption of insulin signaling." (PMID 35453527, 2022).
Insulin resistance (continued). "While the euglycemic insulin clamp is still considered the gold standard for quantifying insulin resistance, in this study we examined other, less invasive and more practical ISIs, which were previously reported to correlate with it well." (PMID 35921366, 2022). "Five studies also evaluated various markers of insulin resistance (IR) for example the Matsuda index and the homeostasis model assessment of insulin (HOMA-IR, HOMA S) and beta cell function like insulinogenic index (IGI)/HOMA-IR, and HOMA B." (PMID 35982427, 2022). "While initial stages of T2D are characterised by insulin resistance, ~30% of patients progress to insulin dependency, with beta-cell mass being reduced due to chronic metabolic stress." (PMID 36291702, 2022). "The HFHFD-induced excessive blood glucose promoted insulin secretion and eventually led to insulin resistance, which triggered lipogenesis and lipid accumulation through SREBP-1 and GPAM." (PMID 36421440, 2022). "Insulin resistance is a condition that affects body cells such as the muscle, liver, and fat cells; consequently, they fail to respond to insulin, even when insulin levels are high." (PMID 35323182, 2022). "Insulin resistance (IR) is a pathological condition in which cells fail to respond normally to insulin." (PMID 35406013, 2022). "The factors inducing insulin resistance were investigated to clarify the mechanism of action of HM-chromanone in promoting glucose uptake in insulin-resistant cells." (PMID 36145191, 2022). "The influence of the supplements on carbohydrate metabolism was measured by glycemia, insulin, and Homeostatic Model Assessment of Insulin Resistance (HOMA-IR)." (PMID 36778595, 2022). "The increase in FFA due to obesity can trigger insulin resistance, which further inhibits insulin signaling and insulin-stimulated glucose uptake in skeletal muscles and increases glucose delivery by the liver." (PMID 36564775, 2022). "He had insulin resistance, as assessed by high fasting insulin (519.4 pmol/L) and C-peptide levels (3.3 nmol/L)." (PMID 35341481, 2022). "The targeted genes were related to the insulin signaling pathway, insulin resistance, the MARK signaling pathway, the PI3K–Akt signaling pathway, and the estrogen signaling pathway." (PMID 35550138, 2022). "Insulin signaling through the PI3K/AKT/mTOR pathways is considered to have an important role in insulin resistance." (PMID 35409099, 2022). "Proinflammatory cytokines including tumor necrosis factor-alpha (TNF-α) and IL-6 have been shown to affect insulin signaling, which can lead to insulin resistance." (PMID 35732620, 2022). "Stress hyperglycemia arises from a highly complex interplay between perturbed proinflammatory cytokines and insulin counter-regulatory hormones, which leads to the hyperproduction of hepatic glucose and the induction of insulin resistance." (PMID 35336774, 2022). "In the present study, 2 weeks of school-based sprint training did not improve fasting markers of metabolic health (fasting glucose, insulin and homeostatic model assessment of insulin resistance [HOMA-IR]) in adolescent girls." (PMID 35992157, 2022). "High levels of insulin, insulin resistance and chronic hyperglycemia contribute to endothelial dysfunction by promoting an inflammatory response, increased oxidative stress, hypercholesterolemia, and progression of atherosclerosis." (PMID 35950156, 2022). "Severe insulin-resistant diabetes (SIRD) was characterised by obesity, severe insulin resistance, high insulin secretion and late onset, but relatively low HbA1c." (PMID 35953726, 2022). "Lipid deposition in skeletal muscle leads to the accumulation of lipid intermediates (diacylglycerol and ceramide) and destroys the insulin signaling pathway, leading to insulin resistance (IR) and the development of type 2 diabetes." (PMID 35237639, 2022). "Despite the high insulin levels and presumed insulin resistance, corticosterone add-on treatment increased the uptake of glucose in WAT and BAT." (PMID 36034417, 2022).
Insulin resistance (continued). "Previous studies have shown that bile acids can activate glucose induced insulin secretion and have a strong correlation with insulin resistance and nonalcoholic fatty liver." (PMID 35606885, 2022). "Existing evidence reveals that trehalose can effectively govern hyperglycemia of diabetic patients via relieving impaired glucose tolerance, mitigating insulin resistance, and reducing postmeal insulin bursts." (PMID 35372500, 2022). "The secondary outcomes included TG, HDL-C, LDL-C, HbA1c, fasting blood glucose, fasting serum insulin, Homeostatic Model Assessment for Insulin Resistance (HOMA-IR), SBP, and DBP." (PMID 35642007, 2022). "GDM in lean women is characterized by insulin resistance in the periconceptional period, and impaired insulin release in mid-late pregnancy." (PMID 36520818, 2022). "Initially, insulin resistance is compensated by increased insulin secretion, but over time, ß-cell dysfunction and diabetes can develop." (PMID 36589440, 2022). "Insulin resistance is determined by impaired sensitivity to insulin in its main target organs, i.e., adipose tissue, liver, and muscle." (PMID 36003642, 2022). "Dysregulated circulating TG and FFA are strongly correlated with insulin resistance, partly by reducing whole-body insulin-stimulated glucose disposal." (PMID 35440636, 2022). "Compared to T0, body weight, insulin resistance, and levels of HbA1c, fasting insulin, insulin resistance, fasting C-peptide, triglyceride, hemoglobin, hematocrit, and platelets were significantly decreased at POM3 and POM6." (PMID 36147694, 2022). "A Consensus Conference has defined insulin resistance (IR) as “the decreased tissue response to insulin-mediated cellular actions, so it is the inverse of insulin sensitivity”." (PMID 36615744, 2022). "Two other studies showed beneficial effects on glucose markers only (fasting glucose, 24h mean glucose levels, and iAUC responses, p<0.05) and the fifth study showed positive effects on insulin markers only (insulin resistance, p<0.05)." (PMID 35300752, 2022). "A key feature that T2DM, obesity and MetS have in common is an impaired response to insulin stimulation in peripheral tissues, better known as insulin resistance." (PMID 35165256, 2022). "Insulin resistance (IR) is defined as reduced insulin sensitivity (IS) and refers to an increased amount of insulin needed to perform its metabolic actions." (PMID 35592754, 2022). "For example, nitric oxide production is lower in response to insulin in insulin resistance, resulting in improper perfusion of skeletal muscle and subsequent impairments of insulin, glucose, and oxygen delivery." (PMID 35277006, 2022). "Due to the insulin resistance in pregnancy, beta cell hypertrophy occurs, but when insulin secretion cannot match the increased insulin demands due to the pregnancy-induced insulin resistance, gestational diabetes occurs." (PMID 35329371, 2022). "Insulin resistance can be partially prevented when vasodilators are given, demonstrating the importance of blood flow for insulin action." (PMID 35277006, 2022). "For example, reducing the expected increase in insulin secretion was secondary to the rise in insulin resistance." (PMID 35163144, 2022). "We propose that IGFBP-1 should be considered as marker of insulin resistance in children, and it is easier to obtain than other commonly used indices of insulin sensitivity." (PMID 35586622, 2022). "Insulin resistance is differentiated by impaired tissue response to insulin and can lead to hyperglycemia and excessive pancreatic insulin secretion leading to balance." (PMID 36248900, 2022). "Insulin resistance (decreased insulin sensitivity) is due to a reduction in the signalling and biochemical actions normally modulated by insulin." (PMID 35968003, 2022). "Under conditions of increasing insulin resistance, the downregulation of lipolysis by insulin can lead to further adipose deposition on hepatocytes, thereby further inducing steatosis." (PMID 36684957, 2022).
Insulin resistance (continued). "The relationship between glucose, insulin, insulin resistance and REE has also been observed in an inter-generational study of 149 families." (PMID 36501139, 2022). "Apparently, the length of telomeres tends to be shorter as insulin resistance increases, mostly because adults who are insulin resistant tend to be more overweight or obese or they tend to have more abdominal adiposity than their counterparts." (PMID 35586815, 2022). "The medication for NAFLD treatment includes lipid-lowering and insulin sensitizing drugs, but these agents have certain disadvantages such as sodium retention, weight gain, increased serum transaminase and insulin resistance after drug withdrawal." (PMID 35999630, 2022). "The glucose‐insulin index established for the analysis of insulin resistance index was observed to be enhanced in HFD‐fed rats when compared with NCD‐fed rats only in the PL group (p < 0.05)." (PMID 35238495, 2022). "Collectively, this study reveals a novel mechanism whereby miR-183-5p induction by SFA impairs insulin signaling and suggests miR-183-5p plays a crucial role in the pathogenesis of hepatic insulin resistance in the background of obesity." (PMID 35328400, 2022). "Researchers also reported reduced cardiac PI3K/Akt insulin activation in T2D mice and a porcine model of diet-induced obesity and insulin resistance." (PMID 35323624, 2022). "Findings of our acute intervention demonstrated that 2-week intervention to a DGA diet was sufficient to reduce fasting glucose, insulin, insulin resistance (HOMA-IR), and blood pressure." (PMID 35458108, 2022). "In elderly patients with DM, insulin signals are reduced because of insulin resistance and reduced insulin secretion, leading to increased protein degradation and decreased protein synthesis, ultimately reducing muscle mass." (PMID 35811950, 2022). "In an AMPK-dependent pathway, metformin promotes small heterodimer partner (SHP) protein production and ameliorates hepatic insulin resistance by regulating gluconeogenesis and insulin sensitivity." (PMID 35955427, 2022). "Studies have evaluated changes in glucose levels, insulin levels, and insulin resistance, as well as the homeostatic model assessment for insulin resistance (HOMA-IR) after the garlic treatment." (PMID 37377647, 2022). "HFD resulted in insulin resistance with significantly elevated fasting glucose levels and significantly elevated fasting insulin levels (P<0.0001 for all comparisons between groups Control vs. HFD+NS)." (PMID 35721744, 2022). "Overall, our results suggest that TLR13 impairs insulin signaling and mediates insulin resistance in response to uremic serum in differentiated muscle cells." (PMID 35088922, 2022). "Endothelial dysfunction is associated with cardiovascular diseases, such as atherosclerosis, hypertension, hyperlipidemia, and insulin resistance, which alter insulin signaling pathways." (PMID 35655279, 2022). "Rooibos extracts also possess demonstrable potential to ameliorate insulin resistance in hepatic cells via the enhancement of sensitivity to insulin." (PMID 36355096, 2022). "It has been estimated that about 80% of NAFLD patients have insulin resistance and that insulin levels are the independent factor for the presence of NAFLD." (PMID 35052811, 2022). "We used the cell line to test its ability to respond to 14 days of stimulation with pathophysiological concentrations of insulin that was observed in the LIRKO mice to simulate the in vivo milieu of insulin resistance." (PMID 35819843, 2022). "This survey indicated that MAFLD patients had greater BMI, lipid, and insulin resistance (e.g., high fasting and postprandial insulin, HOMA-IR, and TyG index) levels and had higher proportions of those who smoked and drank than those without MAFLD." (PMID 35127953, 2022). "During the challenge of insulin resistance, insulin promoted de novo lipogenesis and re-esterification in the liver." (PMID 36558373, 2022).